FBXW7 (F-box and WD repeat domain containing 7)
Diseases named in the same sentence as FBXW7 in open-access papers (continued):
Sharing a sentence is not in itself a finding about the gene and the disease.
breast cancer (continued). "CEBPD has been implicated in MTOR signalling enhancement by transcriptionally suppressing FBXW7, leading to mammary tumour metastasis." (PMID 34954904, 2021). "Coincided with our results, evidence revealed that FBXW7 ectopic expression diminished cell angiogenesis in breast cancer by blocking the HIF‐1α‐VEGF‐A axis." (PMID 33369138, 2021). "The overexpression of FBXW7-185aa resulted in c-Myc degradation and reduced the proliferation and migration abilities of breast cancer cells." (PMID 32781555, 2020). "One of the main oncogenes, c-Myc, which is regulated by FBXW7-185aa, interacts with circ-Amotl1 in breast cancer cells." (PMID 32781555, 2020). "A proof demonstrated that STYX suppresses FBXW7 expression via direct protein–protein interaction in breast cancer cells." (PMID 32239181, 2020). "In breast cancer cells, mTOR is targeted for ubiquitination and consequent degradation by binding to tumor-suppressing E3 ligase, FBXW7." (PMID 32131492, 2020). "FBXW7 is down-regulated not only in breast cancer, but also in 12 other cancers including colon, liver, lung, and prostate cancers." (PMID 31351478, 2019). "Forced expression of FAM83D in nonmalignant cells in culture promoted proliferation and invasion of breast cancer cells and down-regulated the expression of F-box and WD repeat domain-containing 7 (FBXW7), a suppressor of c-Myc, mTOR and C-Jun expression." (PMID 30910840, 2019). "Specifically, we present evidence for the identification of breast cancer-specific SLIs for the tumor suppressor FBXW7." (PMID 31351478, 2019). "It was also reported that HDAC8 was required to maintain Notch1 protein stability by protecting against degradation mediated by Fbxw7 in a deacetylase activity-independent manner in breast cancer." (PMID 31362948, 2019). "In vitro forced overexpression of FBXW7 repressed breast cancer cell proliferation and promoted apoptosis by targeting the oncoprotein, metadherin (MTDH) for proteolysis." (PMID 30791487, 2019). "In particular, in breast cancer cells, 27-HC suppresses FBXW7 transcription leading to an increase of c-Myc protein stability." (PMID 31569395, 2019). "Taken together, the present study suggests that miR-32 promotes proliferation and motility and suppresses apoptosis of breast cancer cells through targeting FBXW7." (PMID 28149200, 2017). "And according to the annotation result of CIViC, we found that FBXW7 deletion enhanced the sensitivity to mTOR inhibitors in breast cancer and renal cell carcinoma." (PMID 29127303, 2017). "Altogether, our findings suggested that miR-32 promotes cell growth and migration of breast cancer cells, at least in part, by targeting FBXW7." (PMID 28149200, 2017). "We found an inverse correlation between the expression of miR-32 and the level of FBXW7 mRNA in breast cancer tissues." (PMID 28149200, 2017). "Data showed that the average level of FBXW7 mRNA was significantly decreased in 19/27 breast cancer tissues when compared with corresponding normal tissues (70.37%, P < 0.05)." (PMID 28149200, 2017). "The purpose of this study was to investigate the effect of miR-32 on cell proliferation, migration and apoptosis and to determine the functional connection between miR-32 and FBXW7 in breast cancer." (PMID 28149200, 2017). "FBXW7 acts as a tumor suppressor involved in the degradation of substrates with oncogenic activity frequently overexpressed in breast cancer such as Cyclin E, c-Myc and AURKA." (PMID 27409838, 2016). "In summary, we show that FBXW7 plays a prominent role in paclitaxel-induced apoptosis by regulating MCL1 and PLK1 levels in breast cancer, as resistant cells loose FBXW7 and accumulate these substrates." (PMID 27409838, 2016).
breast cancer (continued). "In breast cancer, FBXW7 promoter hypermethylation has been identified in 51% of a series of primary tumors." (PMID 27409838, 2016). "Herein, we investigate the role of FBXW7 and relevant substrates in regulating apoptosis induced by paclitaxel in breast cancer cells, their expression in breast cancer tissues, and their potential predictive value in paclitaxel-treated patients." (PMID 27409838, 2016). "The results demonstrate that FAM83D has prognostic value for breast cancer patients and is a novel oncogene in breast cancer development that at least in part acts through mTOR hyper-activation by inhibiting FBXW7." (PMID 24344117, 2013). "The role of FBXW7/hCDC4-β methylation in breast cancer progression and its potential function as a novel biomarker for sensitivity to chemotherapy in breast cancer needs further investigation." (PMID 21122106, 2010). "In line with this, we have preliminary data demonstrating an association between FBXW7/hCDC4-β methylation and high expression of the proliferation marker PCNA in breast cancer (correlation coefficient r = 0.313, P = 0.022 (n = 52, cohort 1))." (PMID 21122106, 2010). "Based on the results above, we next explored the occurrence and role of FBXW7/hCDC4-β methylation in primary breast cancer specimens." (PMID 21122106, 2010). "Mutational inactivation of the FBXW7/hCDC4 tumor suppressor gene (TSG) is common in many cancer types, but infrequent in breast cancers." (PMID 21122106, 2010). "This study investigates the presence and impact of FBXW7/hCDC4 promoter methylation in breast cancer." (PMID 21122106, 2010). "Here, we investigated the importance of FAM83D/FBXW7 interaction in breast cancer (BC)." (PMID 38454442, 2024). "Therefore, in this review, we focused on FBXW7's role in a range of breast cancer malignant behaviors and summarized the pertinent cellular targets, signaling pathways, as well as the mechanisms regulating FBXW7 expression." (PMID 37658431, 2023). "Emerging evidence has suggested that breast cancer progression may be connected to SUMOylation's antagonistic effect on FBXW7-mediated monocarboxylate transporter 4 (MCT4) ubiquitination." (PMID 37658431, 2023). "FBXW7 has a wide range of breast cancer targets, and imbalance in its binding to oncogenic substrates may drive tumor spread." (PMID 37658431, 2023). "If the key issues of miRNA transport vectors and miRNA efficacy in cancer cells can be addressed in the future, mimics or antagonists targeting miRNAs upstream of FBXW7 may slow breast cancer progression." (PMID 37658431, 2023). "Furthermore, we also summarize breast cancer therapeutic strategies targeting FBXW7, providing novel perspectives for the exploration and innovation of clinically targeted agents and specific diagnostic markers." (PMID 37658431, 2023). "Metastatic breast cancer correlates with poor clinicopathological phenotype of invasion and drug resistance, downregulation of FBXW7 expression attenuates the ubiquitination and destruction of associated substrates, hence boosting breast cancer invasion and metastasis." (PMID 37658431, 2023). "An exploration of whether additional mechanisms regulate the intracellular expression of FBXW7 will help identify promising new breast cancer therapeutic targets." (PMID 37658431, 2023). "In summary, FBXW7 expression correlates with breast cancer development." (PMID 37658431, 2023). "Conversely, inhibition of miR-182 increased the FBXW7 protein levels in human breast cancer cells." (PMID 36998461, 2023). "Here, we summarize the therapeutic strategy for targeting FBXW7 in breast cancer." (PMID 37658431, 2023). "This implies that FBXW7 mechanisms for controlling drug resistance in breast cancer are intricate." (PMID 37658431, 2023). "Indeed, AEG-1 was demonstrated to interact with FBXW7 for ubiquitination in both breast cancer cells 7 and liver cancer cells, implying a conserved protein degradation pathway related to AEG-1." (PMID 36276642, 2022).
breast cancer (continued). "In addition, SETD3 regulates the expression of multiple breast-cancer-associated genes, such as ACTB, FBXW7, Fascin, eNOS, and MMP-2, which suggests it as a promising biomarker for breast cancer prognosis." (PMID 35912180, 2022). "Indeed, a recent study reported that FBXW7-mediated AEG-1 ubiquitination significantly suppresses breast cancer cell proliferation by attenuating AEG-1 protein stability." (PMID 36276642, 2022). "The anti‐angiogenesis role of FBXW7 has been identified in breast cancer." (PMID 33369138, 2021). "The over-expression of FBXW7 in breast cancer cells could inhibit EMT and the migratory aptitude of these cells." (PMID 34804971, 2021). "STYX has been associated with cell proliferation, migration, invasion, and apoptosis in colorectal cancer cells and a range of studies have indicated that STYX acts as a latent oncogene that inhibits apoptosis in colorectal and breast cancer, mainly by binding to FBXW7." (PMID 33822486, 2021). "Studies have affirmed that an oncogene FAM83D (family with sequence similarity 83, member D) present on chromosome 20q has a significant role in breast cancer development by downregulating FBXW7 resulting in amplification of its oncogenic substrates such as mTOR." (PMID 30791487, 2019). "Moreover, downregulation of FBXW7 in MDA-MB-468R breast cancer cell induced resistance to the drug paclitaxel by the accumulation of its substrates myeloid cell leukemia 1 (MCL-1) and polo-like kinase 1 (PLK1)." (PMID 30791487, 2019). "In breast cancer cells, it targets the E3 ubiquitin-protein ligase FBXW7 (F-box and WD repeat domain-containing 7), whereas in prostate cancer cells its targets are two negative regulators of HIF-1 signaling: PHDs (prolyl hydroxylase domain enzymes) and FIH1 (factor inhibiting HIF-1)." (PMID 31757094, 2019). "Additionally, it has also been found that miR-32 induced cell proliferation, migration and evaded apoptosis in breast cancer in vitro by downregulating FBXW7." (PMID 30791487, 2019). "In addition, STYX regulates apoptosis in breast cancer cells and HeLa cells through cross-talk with FBXW7." (PMID 31608184, 2019). "Another negative regulator of FBXW7, miR-32 was found to be upregulated in breast cancer cells, and directly binds to the 3′-UTR region of FBXW7 and hence reducing FBXW7 expression which resulted in increased breast cancer cell proliferation, migration and inhibited apoptosis." (PMID 30791487, 2019). "Accumulated evidence has suggested that inactivation or downregulation of FBXW7 may lead to the development of chemoresistance in various cancers, such as breast cancer, colorectal cancer, gastric cancer, and non-small cell lung cancer." (PMID 30791487, 2019). "In addition, one report finds that 80% of breast cancer cell lines harbor alternatively spliced isoforms of FBXW7." (PMID 30086763, 2018). "Since FBXW7 can target different substrates in a cell-context dependent manner, further studies are needed to identify the role of FBXW7 in different subtypes of breast cancer." (PMID 30086763, 2018). "Depletion of FBXW7 by shFBXW7 could promote the proliferation and motility,supress apoptosis of breast cancer cells." (PMID 28149200, 2017). "In addition, miR-32 induced down-regulation of FBXW7 and regulated the proliferation, migration and apoptosis capability of breast cancer cells." (PMID 28149200, 2017). "Moreover, FBXW7 mRNA levels in breast cancer cases were inversely correlated with miR-32 expression." (PMID 28149200, 2017). "Furthermore, an inverse correlation was found between the expressions of miR-32 and FBXW7 mRNA levels in breast cancer tissues." (PMID 28149200, 2017). "Our study showed that inhibition of FBXW7 mRNA expression could promote the proliferation and migration, and suppress apoptosis of breast cancer cells." (PMID 28149200, 2017). "Interestingly, deletion of the last ten exons of FBXW7 was previously reported as a founding event in a basal-like breast cancer." (PMID 27923045, 2016).
breast cancer (continued). "To analyze FBXW7 expression and its relation to the relative abundance of substrates, and with prognostic variables in breast cancer, we performed immunohistochemistry for FBXW7, AURKA, Cyclin E, MCL1 and PLK1 in tissue microarrays containing up to 296 samples of breast carcinomas." (PMID 27409838, 2016). "To further investigate whether FBXW7 expression correlated with its substrates in breast cancer tissues, we decided to study the protein levels of Cyclin E, MCL1, AURKA and PLK1 in these samples." (PMID 27409838, 2016). "We also looked at the relative expression of FBXW7 and its substrates in a series of breast carcinoma tissues to establish whether these proteins could be valuable prognostic markers and predict patient response to paclitaxel treatment." (PMID 27409838, 2016). "Interestingly, our analysis suggests that MYC and FBXW7 expression are mildly but significantly positively correlated, specifically in the Luminal A-subtype of breast cancers." (PMID 25669969, 2015). "Our data on two different groups of breast cancer patients and from a meta-analysis, in which Notch signaling is constitutively activated despite high levels of Fbxw7, strongly support this hypothesis." (PMID 24357640, 2014). "Notably, the average expression value of NDT gene signature was contingent on PIN1 mRNA levels, while FBXW7 was non influential, therefore highlighting the biological dominance of Pin1 over Fbxw7α in regulating Notch signaling in breast cancer." (PMID 24357640, 2014). "In the present study, we examined the possibility that FBXW7/hCDC4 expression is epigenetically inactivated through promoter specific hypermethylation in breast cancer, a tumor type where Fbxw7/hCdc4 mutations are not commonly observed." (PMID 21122106, 2010). "Thus, miR-32-5p likely regulates c-MYC through FBXW7 degradation—a pathway conserved in breast cancer but never linked to c-MYC until now." (PMID 40711670, 2025). "However, additional research into the mechanisms through which FBXW7 influences the biological behavior of breast cancer is still required, and exploring the suppressive effects of FBXW7 in depth might provide new targets for anti-breast cancer therapy." (PMID 37658431, 2023). "Thus, targeting FBXW7 ablation to stimulate DTCs from dormancy to proliferation may be a viable treatment to overcome breast cancer medication resistance." (PMID 37658431, 2023). "The FBXW7 gene (Gene ID: 55294) maps to chromosome region 4q31.3 including 18 exons, where mutations are frequently detected in multiple human cancers, such as colorectal cancer (CRC), ovarian cancer, breast cancer (BC), endometrial cancer, and human T-cell acute lymphoblastic leukemia (T-ALL)." (PMID 35515121, 2022). "In addition, researches have demonstrated that FAM83D may act as a carcinogenic role by suppressing the invasion and proliferation of hepatocellular carcinoma and inhibiting the cell cycle of lung adenocarcinoma by suppressing FBXW7 in breast carcinoma." (PMID 35489022, 2022). "Furthermore, our results imply that high expression of miR-32 may contribute to the development of breast cancer through targeting FBXW7." (PMID 28149200, 2017). "Furthermore, we identified FBXW7 as a direct target of miR-32 in breast cancer cell lines." (PMID 28149200, 2017). "Fbxw7 has been characterized as a general tumor suppressor in human cancer, and reduced Fbxw7 expression is often observed in multiple human cancers, including breast cancer, colorectal cancer, gastric cancer, prostate cancer, pancreatic cancer and hepatocellular carcinoma." (PMID 26461473, 2015). "Interestingly, although methylation associates with high-grade tumors, univariate and multivariate analysis suggest that FBXW7/hCDC4-β promoter methylation might be a favorable prognostic marker in breast cancer." (PMID 21122106, 2010). "Activated ERK1/2 triggers FBXW7 down-regulation, which enhances HSF-1 binding to MDR1, leading to the emergence of paclitaxel-resistant breast cancer cells." (PMID 37658431, 2023).
breast cancer (continued). "The major finding of this study is that miR-92b regulates FBXW7, a previous well described tumor suppressor gene in multiple types of cancers such as acute lymphoblastic leukemia (T-ALL), colorectal cancer, breast cancer, and brain cancer." (PMID 37752997, 2023). "Breast cancer cells tend to proliferate when ß‐actin, FOXM1, FBXW7, Fascin, eNOS, MMP‐2 and HER2‐receptor are expressed or stimulated." (PMID 37697969, 2023). "In breast cancer, miR-223 can directly bind to the 3′UTR of the tumor suppressor gene FBXW7 and consequently facilitate the infiltration and spread of breast cancer cells." (PMID 37465640, 2023). "F-box and WD repeat domain-containing 7 (FBXW7) is a member of the E3 family of ubiquitin ligases and has been downregulated in various human cancers, including HCC, colon cancer, and breast cancer." (PMID 36159747, 2022). "In breast cancer cells, STYX has been found to suppress FBXW7 expression through direct protein‐protein binding." (PMID 33822486, 2021). "Mounting evidences have revealed the role of F-box proteins in regulating EMT in multiple types of tumors, including FBXW7 in lung cancer and gastric cancer, FBXO11 in breast cancer and gastric cancer, and FBXO45 in prostate cancer and PCa." (PMID 34249081, 2021). "A majority of study testified STYX acts as a latent oncogene, suggesting that STYX restrained cell apoptosis in colorectal and breast cancer by binding F-box and WD40 domain protein 7 (FBXW7, also called hCDC4, Fbw7) protein." (PMID 32239181, 2020). "Of note, FBXW7 and PEMT are both down-regulated in breast cancer and they share a proposed SLI in HYGIN." (PMID 31351478, 2019). "Further studies have revealed that C/EBPδ inhibited the expression of FBXW7, thereby increasing the activities of the FBXW7 substrates such as mTOR and HIF-1α and potentiated metastasis in mammary tumors." (PMID 30791487, 2019). "Studies have indicated that miR-32-5p plays an oncogenic role in the growth and invasion ability of breast cancer cells by directly silencing PHLPP2 and FBXW7." (PMID 29661250, 2018). "This prompted us to consider FBXW7 as an important mediator of the paclitaxel response through the control of MCL1 and PLK1 degradation in breast cancer." (PMID 27409838, 2016). "We investigated the role of FBXW7 and their substrates MCL1 and PLK1 in regulating the apoptotic response to paclitaxel treatment in breast cancer cells and their expression in breast cancer tissues." (PMID 27409838, 2016). "One recent study demonstrated that CEBPD directly inhibits expression of the tumor suppressor FBXW7, resulting in a consequent enhancement of mTOR/AKT/S6K1 signaling, which further suggests CEBPD is necessary for metastatic progression of mammary tumors." (PMID 26307680, 2015). "We next stained serial sections of the second group (38 TNBC samples) of breast cancer tissues with anti-N1-ICD, anti-Pin1 and anti-Fbxw7 antibodies." (PMID 24357640, 2014). "Consistent with the previous findings, the FAM83D expression was higher in the breast cancer tissue compared to the non-cancerous tissues, but the expression of FBXW7 is lower in breast cancer tissues than that in adjacent tissues." (PMID 38454442, 2024). "In HCC and breast cancer, ANXA2 was found to interact with FBXW7 and MIEN2 respectively." (PMID 38658569, 2024). "Multiple studies have since reported that F-box (FBX) family proteins (FBXL14, FBXO45, FBXO11, FBXO22, FBXW7, FBXL5 and FBXW7) inhibit EMT, metastasis and progression of breast cancer, gastric cancer and non-small lung cancer through proteasome-mediated Snail degradation." (PMID 36675208, 2023). "FBXW7 liberation from C/EBPδ transcriptional repression promotes polyubiquitination of endogenous mTOR and HIF-1α protein binding and inhibits intracellular accumulation, reducing lung metastasis in breast cancer model mice under hypoxic adaptation." (PMID 37658431, 2023).